AFP (alpha fetoprotein)
Diseases named in the same sentence as AFP in open-access papers (continued):
Sharing a sentence is not in itself a finding about the gene and the disease.
germinoma (continued). "In the HR group (n = 58), the pathologic diagnosis of 14 patients was germinoma, but they were classified into the HR group due to serum or CSF-β-HCG levels being above 50 mIU/mL (n = 12), or abnormal AFP levels (n = 2)." (PMID 33036578, 2020). "NGGCTs are diagnosed if the AFP or HCG level are higher than certain limits defined in the CSF or serum, but some germinomas can have positive HCG in lower levels and are considered a higher risk group when compared with those that are negative for markers." (PMID 31860688, 2019). "These biomarkers are beneficial in differentiating pure germinomas from non-germinomatous GCTs, as a pure germinoma usually shows no rise in AFP or HCG." (PMID 41523526, 2025). "Serum and CSF tumor markers, such as AFP or β-HCG, are crucial in diagnosing germinomas." (PMID 40805263, 2025). "Four patients with positive BHCG levels below 50 mIU/mL were diagnosed as germinomas; three patients with BHCG levels greater than 50 mIU/mL and one with positive AFP were diagnosed as NGGCT; and this last patient had histologic confirmation with surgery after chemotherapy." (PMID 39035740, 2024). "Therefore, the second-step nomogram model was developed from age, AFP/HCG, tumor size, boundary, and anterior cardioid extension to identify germinoma." (PMID 37706201, 2023). "If a pineal region tumor is homogeneously enhanced and has the classic appearance of germinoma on MRI with isointensity relative to CSF and elevated β-HCG and AFP, which is essential for the diagnosis of germinoma, a test dose of 5 Gy may be administered." (PMID 38066820, 2023). "For example, the majority of germinomas are AFP/HCG “marker-negative” and as they are only metastatic in less than 20% of cases (by imaging and/or cytology), CSF cytology alone has a very low diagnostic yield." (PMID 32642701, 2020). "Although measuring the serum alpha-fetoprotein and human chorionic gonadtropin is important, they are often negative in pure germinomas, as in our case." (PMID 26759273, 2016). "Keita Terashima extended these observations, showing that levels of these microRNAs were elevated in the cerebrospinal fluid (CSF) when malignant CNS GCT diagnosis, including in AFP/HCG marker-negative germinomas." (PMID 23861728, 2013). "On the other hand, in a pure germinoma, AFP is not elevated." (PMID 39723268, 2024). "In the largest data set so far on miRNAs as liquid biomarkers in iGCT, we underlined the utility of miR-371a, miR-372, miR-367 and miR-302d in patient serum for diagnosis of iGCT, a result particularly noteworthy in germinoma patients negative for other biomarkers, such as AFP and ß-HCG." (PMID 35171328, 2023). "However, in pure germinomas, only HCG is secreted while AFP levels are normal in serum and CSF." (PMID 35130327, 2022). "Furthermore, the determination of alpha-fetoprotein (AFP) and beta-human chorionic gonadotropin (hCG-ß) levels in serum and CSF may be particularly helpful in the initial differentiation between germinomas and non-germinomatous germ cell tumors." (PMID 37036624, 2023). "Levels of placental alkaline phosphatase are relatively sensitive and specific for a diagnosis of germinoma and are particularly helpful when serum and CSF levels of β-HCG and AFP are nondiagnostic." (PMID 37519792, 2023). "Out of 25 patients, two patients without hydrocephalus were AFP and β-HCG negative in serum and CSF but confirmed to have a germinoma by biopsy." (PMID 32504201, 2021). "The other case was originally a germinoma (with serum ß-HCG < 50 mlU/ml, negative serum AFP and negative CSF markers and cytology) that recurred as a NGGCT with positive serum and CSF markers (both ß-HCG and AFP) and CSF positive cytology." (PMID 31860688, 2019).
Ascites (36 papers, 2013 to 2026). Accumulation of fluid in the peritoneal cavity (between the layers of the peritoneum that lines the abdomen). "Specifically, high levels of serum creatinine, tumor size, bilirubin, AFP, and moderate ascites were associated with increased risk, whereas lower values corresponded to lower risk." (PMID 41536859, 2026). "Higher mortality was noted among patients with elevated AFP >400 ng/mL, relapse, abdominal ascites, and a CLIP score." (PMID 38374854, 2024). "In this investigation, elevated AFP levels exceeding 400 ng/mL, relapse, the presence of ascites, and a higher CLIP score demonstrated statistically significant associations with mortality." (PMID 38374854, 2024). "Univariate analysis revealed that age, the occurrence of complications (i.e. infection, UGB, ascites, and HE), and the levels of TBIL, AFP, INR, TC, HDL-C, and D-dimer were significantly associated with 90-day mortality (p < 0.05)." (PMID 36964486, 2023). "The Cox model revealed that OS is related to Child-Pugh scores, CNLC stage, ascites, AFP, caudate, and anti-HCV." (PMID 37304009, 2022). "This AUROC remained higher for the GALAD score irrespective of disease etiology (US had a lower AUROC in patients with alcoholic liver disease), AFP values, or with the presence of ascites in which the US performance is usually affected." (PMID 32492896, 2020). "The univariate analysis revealed that nine variables including the baseline serum PLT level, the baseline CRP level, the baseline AFP level, the tumor size, the tumor number, the 8-and-14 grade, ascites, the ALBI grade, and the ALBI-AS grades were evaluated to be associated with overall survival." (PMID 35845571, 2022). "For OS, age > 65 years, Child–Pugh liver function classification B, the presence of ascites, microvascular invasion, high ANXA2 expression, AFP, bilirubin and AST > upper limit of normal were associated with short OS in the univariate Cox proportional analysis." (PMID 34575275, 2021). "Other initially intriguing markers that did not appear to have a significant influence in our model include CSPH, bilirubin levels, the presence of portal thrombosis, ascites, ACLD, encephalopathy, or AFP levels." (PMID 38396445, 2024).
viral infection (35 papers, 2004 to 2025). "Similarly, in the GEO cohort, CEP55 expression was associated with tumor stage, survival status, tumor size, viral infection, and serum AFP level (p < 0.05)." (PMID 37484531, 2023). "In addition, the majority of HCC patients are caused by virus infection, so for the first time, our team examined the prognostic value of AFP among them with virus-related HCC." (PMID 34976804, 2021). "When using AFP as a biomarker, a modified threshold that considers various factors, such as disease etiology/spectrum, underlying viral infection, age, and race/ethnicity for different populations may improve diagnostic accuracy." (PMID 30675135, 2019). "Thus, taking viral infection into account when setting AFP biomarker thresholds may improve assessment of HCC risk in the US versus other countries." (PMID 30675135, 2019). "On the other hand, CLASS B had a higher proportion of mid to late-stage samples, higher AFP expression levels, and a higher frequency of viral infection." (PMID 38728362, 2024). "The IMbrave150 study indicated that the main factors affecting the long-term survival of patients with PFS and OS after treatment with atezolizumab plus bevacizumab included viral infection and AFP levels." (PMID 37928530, 2023). "In the TCGA cohort, patients in the low GBPs‐score group were closely related to worse TNM stage and grade, higher AFP level, and higher percentages of tumor invasion and virus infection." (PMID 37551111, 2023). "In the TCGA-LIHC cohort, samples with high AFP expression, viral infection, vascular invasion, advanced histologic grade, and TNM staging were significantly higher in the high HAscore group." (PMID 35145517, 2022). "PTP4A3/PRL-3 mRNA was significantly correlated with virus infection (P = 0.0422), serum AFP (P = 0.0047), PIVKA-II (P = 0.0259), portal vein invasion (P = 0.0156), and vascular invasion (P = 0.0192)." (PMID 23064776, 2013). "In addition, no intergroup differences were noted in terms of the classification of serum ALT, ALB, TB, PT, and AFP levels; Child-Pugh score; status of viral infection; and BCLC stage." (PMID 32280472, 2020). "Different viral infection and treatment may be a confounder for AFP prognostic assessment in HCC patients." (PMID 31829979, 2019). "Subgroup stratification considered gender, age, sorafenib-responsiveness and drug tolerability, viral infection, macrovascular invasion, HCC extrahepatic spread, performance status, and alpha-fetoprotein levels." (PMID 34146196, 2022). "We also analyzed the anti-ATIC autoantibody and AFP, according to tumor-node-metastasis (TNM) staging, tumor size, and viral infection." (PMID 33352757, 2020). "The results from several studies show that the detection of AFP-specific CD8 T cells is restricted to HCC patients, but does not correlate with elevated serum AFP concentrations, vascular invasion or type of viral infection." (PMID 20087354, 2010). "The HAscore was higher in the groups with high AFP expression, vascular invasion, viral infection, multiple nodules, advanced histologic grade, TNM staging, and CLIP staging." (PMID 35145517, 2022). "Previous studies have shown that commonly used clinicopathological parameters (such as age, TNM staging, sex, viral infection, and AFP levels) were not sufficient to accurately predict prognosis of patients." (PMID 32611831, 2020). "Contrary to anti-ATIC response, HCC patients without viral infection showed low AFP levels (10% compared to 80%)." (PMID 33352757, 2020). "The underlying pathological mechanism might be that the lack of expression of AFP in the absence of hepatitis B and C virus infections could lead to good clinical pathological characteristics." (PMID 35293607, 2023). "We found that genotype *2 of the LAPTM4B gene was significantly associated with recurrence, poor histopathologic differentiation, higher TNM stage and portal vein invasion (P<0.05), but not with viral infection status, tumor size or serum AFP level, age or gender (P>0.05)." (PMID 22509374, 2012).
viral infection (continued). "In contrast, for patients without viral infection, with ECOG PS = 0, without EHS, and with AFP ≥400 ng/mL, dual ICI therapy was more beneficial, particularly in patients with AFP ≥400 ng/mL (HR = 0.66, 95% CI 0.52-0.83)." (PMID 41451207, 2025). "The clinical features of both groups were not significantly different in terms of age, gender, serum AFP levels, differentiation of HCC, tumor multiplicity, vascular invasion, TNM factors and stages, histology of the non-tumor liver, liver function, or the type of viral infection." (PMID 28114424, 2017).
colon carcinoma (34 papers, 2012 to 2025). "AFP-producing colon cancers are highly aggressive malignancies with poor prognoses as compared with their non-AFP-producing variant." (PMID 36742145, 2023). "Carcinoembryonic antigen (CEA) and α-fetoprotein (AFP) are important biomarkers for diagnosis and prognosis of colon cancer." (PMID 36742145, 2023). "The increased levels of pro-inflammatory cytokines (TNF-& IL-1β), and tumor markers (CEA, CA19.9 and AFP) matched with a decrease in apoptotic biomarkers (CD4+) in colon cancer-bearing rats are in line with other earlier research." (PMID 36294905, 2022). "Immunohistochemical analysis confirmed that CXCR4 and AFP levels were increased in liver metastases compared to primary colon tumors." (PMID 36591565, 2022). "In conclusion, we report on an AFP-producing colon cancer diagnosed at an early stage, whereby early detection enabled a complete resection of the carcinoma." (PMID 25962419, 2015). "These markers are cancer antigen 19-9 (CA19-9), also known for pancreatic, gastric and colon cancer, α-fetoprotein (AFP), also known for ovary, testis and liver cancer, and migration inhibitory factor (MIF), also known for gastric, prostate, and colon cancer." (PMID 23202969, 2012). "According to the current research, administering LME to colon cancer-model rats significantly reduced their levels of AFP, CEA, and CA 19.9, as well as immune-inflammatory markers (TNF-α and IL-1β) matched with the development of apoptotic biomarker (CD4+), compared to the control group." (PMID 36294905, 2022). "Here, we report a rare case of colon cancer in a patient with an elevated serum AFP level." (PMID 26976278, 2016). "Further accumulation of data and investigation of AFP-producing colon cancer is necessary." (PMID 25962419, 2015). "Additionally AFP-producing colon cancer is extremely rare, with only 11 reported cases in English literature." (PMID 25962419, 2015). "Furthermore, overexpression of LIN28 is associated with high serum a-fetoprotein (AFP) levels and high-grade HCC tumors as well as a reduced overall survival and increased probability of tumor recurrence in colon carcinoma." (PMID 24475120, 2014). "One-month post-surgery, the expression rates of TSGF, CEA, and AFP drastically declined, thus suggesting the possibility of using TSGF as a biomarker to evaluate the effect of the radical operation on colon cancer." (PMID 37646066, 2023). "The colon cancer group showed a marked increase in serum levels of CA19.9, CEA, AFP, TNF-α, IL-1β, and colon DNA-fragmentation matched with a decrease of CD4+ compared with the control group." (PMID 36294905, 2022). "In clinical diagnosis and treatment, colon cancer status is typically determined through imaging or abnormally elevated serum tumor markers such as CEA, AFP, CA125, CA199." (PMID 30884206, 2019). "In this case, the poorly differentiated carcinomatous component was positive for epithelial and colon cancer markers (CK7, CK20, EMA, CDX2, and AFP) and the spindle-shaped pleomorphic sarcomatous component was strongly positive for vimentin, but negative for epithelial markers." (PMID 33765265, 2021). "Single or a small number of serum-based biomarkers indicative of cancer progression, such as prostate-specific antigen (PSA), alpha-fetoprotein (AFP), CA-125, CA-15.3, CA-19-9, or CEA for prostate, liver, ovary, breast, pancreas, or colon cancer, are currently used." (PMID 23401773, 2013). "AFP, hep-1 and glypican-3, the well-used biomarkers for HCC, were negative and two well-known tumor markers for colon cancer, CK20, CDX2 were positive, clearly indicating that xenograft tumor were derived from intestinal tissue." (PMID 30214379, 2018).
End Stage Liver Disease (34 papers, 2013 to 2026). Final stage of a liver disease when the liver failure is irreversible and LIVER TRANSPLANTATION is needed. "Traditional scoring systems, including Child–Pugh, Albumin–Bilirubin, Model for End-Stage Liver Disease (MELD), MELD-Na, MELD 3.0, and Alpha-fetoprotein scores, are widely used but often fail to provide precise risk assessments." (PMID 41536859, 2026). "High alpha-fetoprotein (AFP), high C-reactive protein (CRP), low albumin, and an increase in Model for End-stage Liver Disease (MELD) and Child-Turcotte-Pugh (CTP) scores were found to have a negative impact at three months." (PMID 40385925, 2025). "These markers include tumor burden, liver function, and physical status, which are further refined by Alpha-Fetoprotein (AFP), Albumin–Bilirubin Index (ALBI) score, Child–Pugh, and Model for End-Stage Liver Disease (MELD)." (PMID 40075750, 2025). "This study also identified a model for end-stage liver disease (MELD) scores and alpha-fetoprotein (AFP) levels as prognostic factors in untreated patients, independent of the BCLC stage." (PMID 37035191, 2023). "The median model for end-stage liver disease (MELD) score was 9 (IQR 7–11), and the median alpha-fetoprotein (AFP) was 19.4 ng/dL (IQR 4.7–310.9)." (PMID 37666940, 2023). "The median AFP and pre-treatment HCV-RNA levels were 3.8 ng/mL and 905,000 IU/mL, respectively, and the median Child–Pugh and model for end-stage liver disease (MELD) scores were 5.0 and 7.0, respectively." (PMID 37629725, 2023). "Retrospective studies have shown that combinations of the Model of End Stage Liver Disease (MELD)c score, Milan Criteria, and alpha fetoprotein (AFP) biomarker levels at diagnosis can be used to stratify an ideal bridge to LT candidates." (PMID 35406456, 2022). "The alpha fetoprotein (AFP), albumin, and GGT levels were higher in the HCC group; however, total bilirubin, INR, model for end-stage liver disease (MELD) scores, and Child–Pugh scores were higher in the non-HCC group (P < .001)." (PMID 32176089, 2020). "The available variables for analysis are age at diagnosis, gender, serum alpha-fetoprotein (AFP), Child–Pugh score, the model for end-stage liver disease (MELD), tumor size, tumor number, grade, and tumor stage according to the American Joint Committee on Cancer (Stage AJCC)." (PMID 35352293, 2022). "Variables included TACE type/number, tumor type, microcatheter location, Child-Pugh, baseline tumor burden (tumor number/total/largest size), vessel invasion, alpha-fetoprotein, Eastern Cooperative Oncology Group (ECOG) performance status, and Model for End-Stage Liver Disease (MELD) score." (PMID 34804911, 2021). "The clinical features of NR1H4-related cholestasis include neonatal onset with rapid progression to end-stage liver disease, early onset vitamin K-independent coagulopathy, low-to-normal serum GGT, elevated serum alpha-fetoprotein and undetectable liver BSEP expression." (PMID 26888176, 2016).